EPOR (erythropoietin receptor)
Diseases named in the same sentence as EPOR in open-access papers (continued):
Sharing a sentence is not in itself a finding about the gene and the disease.
ulcers (1 paper, 2022). "Due to skin lesions, such as petechial hemorrhages and the presence of ulcers, caused by P. salmonis in salmonids, the EPOR could be a candidate gene involved in defense mechanisms." (PMID 36672855, 2022).
uremia (1 paper, 2021). A clinical syndrome associated with the retention of renal waste products or uremic toxins in the blood. "On the other hand, uremia from pre-existing renal injury might interfere with EPOR and the immunomodulatory functions of EPO along with uremia-induced dysfunctions in other organs." (PMID 34831360, 2021).
Ureteral obstruction (1 paper, 2021). Obstruction of the flow of urine through the ureter. "The activation of EPOR/βcR was observed to decrease the expression of α-smooth muscle actin (α-SMA), a specific marker for myofibroblasts, and deposition of the extracellular matrix in rodent IR injury and unilateral ureteral obstruction models." (PMID 34276689, 2021). "In addition, CEPO, which specifically recognizes EPOR/βcR, decreased α-SMA expression, a marker of myofibroblasts, in a 14-day rat AKI model induced by unilateral ureteral obstruction." (PMID 34276689, 2021).
vascular malformation (1 paper, 2025). A non-neoplastic disorder that is the result of defects of vascular morphogenesis. "Thus, we cannot exclude a contributory role of EPOR to the congenital vascular malformation exhibited by the patient, and this possible association needs further investigations." (PMID 40259928, 2025).
tumor (99 papers, 2001 to 2026). "Both human cancer and murine stromal cells comprising the tumor expressed fewer mitochondria, indicating that the loss of EPOR in tumor cells affects the whole tumor microenvironment." (PMID 36052260, 2022). "One histological study showed that EPOR is expressed in more than 70% of NB tumors and has higher expression in lymph node metastases than the primary tumor, but high EPOR protein expression was associated with favorable outcomes for NB patients." (PMID 34556815, 2021). "CCA associated endothelial cells highly express erythropoietin receptor (EpoR) that bind to liver‐cell‐released erythropoietin (Epo) in the tumour microenvironment, thus promoting proliferation, survival, and invasion of CCA cells." (PMID 30394682, 2019). "Contrary, the high level of EpoR expression found in DLD-1 tumors was linked directly with tumor size after Epo administration." (PMID 27543111, 2016). "Based on these findings, we thought that the HeLa-based system appears to be the most suitable to investigate the significance of the Epo-EpoR pathway in cervical SCC-associated tumor microenvironment particularly in vivo." (PMID 25874769, 2015). "High EPOR expression in patients with OSCC was associated with tumor progression in the present comprehensive study." (PMID 22639817, 2012). "High EPOR expression in OSCC is associated with an aggressive tumor behavior and poorer prognosis in the univariate analysis among patients with OSCC." (PMID 22639817, 2012). "Such a sol-EpoR variant is known to rapidly accumulate up to the nanogram level in the growth medium of tumor cells as soon as 1.5 hours after medium renewal." (PMID 21829709, 2011). "Although rhEpo has been implicated in the regulation of tumor growth, the precise role of rhEpo/EpoR in human cancers is not well understood." (PMID 22188703, 2011). "A recent workshop at the National Cancer Institute (December 2007) concluded that conflicting and confounding data exist regarding the expression and function of EpoR protein on tumour cells and the association of EpoR with disease progression." (PMID 20051958, 2010). "Since EPOR transcripts were detected in tumour cells, albeit at low levels, we investigated the association between transcript levels and expression of EpoR at the cell surface." (PMID 18349818, 2008). "The high recurrence of Spi-1 insertional mutation in Friend tumor cells suggested that Spi-1 overexpression was cooperative with the constitutive signaling from gp55/EpoR and sf-Stk/EpoR complexes to induce the malignant transformation of the proerythroblast." (PMID 18983647, 2008). "When implanted into window chambers and monitored serially by fluorescent and transmitted light intravital microscopy, EPOR-R129C expression was associated with a significant enhancement of tumor-cell induced neovascularization and growth in all chambers." (PMID 17579721, 2007). "In contrast, EPOR expression varied based on culture duration rather than oxygen levels in the 786-O cells, indicating that EPOR expression was higher in response to reduced oxygen in tumor cells, while in tumor cells with a mutation in VHL, it depended on the length of cultivation." (PMID 40332447, 2025). "Interestingly, murine stromal cells in EPOR-deficient A549 tumors also had fewer mitochondria than those in the control tumors, suggesting that tumor EPOR controls mitochondria on a cell-by-cell basis as well as in a paracrine fashion." (PMID 36052260, 2022). "Besides, CCA-associated endothelial cells highly express the erythropoietin receptor, which binds to cell-released erythropoietin in the tumor immune microenvironment, thus promoting proliferation, survival, and invasion of CCA cells." (PMID 35983036, 2022). "Nevertheless, detailed mechanisms still remain unclear as to how the Epo-EpoR pathway is involved in tumorigenesis as well as tumor-associated microenvironment such as angiogenesis and immune responses." (PMID 25874769, 2015).
tumor (continued). "Moreover, in the liver of nude mice receiving VF/EpoR cells, the disruption of hepatocyte arrangement in lobules caused by infiltrated tumor cells disappeared by DFMO treatment." (PMID 23300995, 2013). "Continuous high expression of Epo and EpoR in primitive mesenchymal cells may lead to cellular proliferation via autocrine stimulation and become a critical pathogenic step in tumor formation." (PMID 23833638, 2013). "Furthermore, local rhEPO application in window chambers or stable expression of a constitutively active EPOR mutant (EPOR-R129C) might have a potential to stimulate tumor angiogenesis, associated with significant stimulation of tumor growth." (PMID 28703764, 2017). "In orthotopic tumor xenograft studies, EPOR-R129C expression significantly promoted tumor growth associated with increased expression of Ki67 proliferation antigen, enhanced microvessel density, decreased tumor hypoxia, and increased phosphorylation of extracellular-regulated kinases ERK1/2." (PMID 17579721, 2007). "When active, EPOR triggers processes within cells that contribute to tumour development, facilitating cell survival, proliferation, and angiogenesis." (PMID 41514679, 2026). "In tumors expressing HIF1A, elevated EPO expression contributes to tumor progression by stimulating EPOR and activating downstream signaling pathways, such as JAK2-STAT5." (PMID 40332447, 2025). "In cases where HIF1A is expressed, there was an upregulation of JAK2 and STAT5A proteins in tumor tissue, alongside EPOR." (PMID 40332447, 2025). "As a result, EPO produced by tumors can stimulate the EPO/EPOR signaling pathway in macrophages found in a tumor microenvironment (TME)." (PMID 41012526, 2025). "EPOR levels in tumor tissue were reduced compared to surrounding healthy tissue in the absence of HIF1A." (PMID 40332447, 2025). "EPOR expression in both normal and malignant tissues implicates it in mitochondrial regulation and tumor progression." (PMID 41012526, 2025). "When HIF1A was present in the tumor tissue, the EPOR expression was inducted compared to the HIF1A-negative tumors and the level was similar to that of the surrounding normal tissue." (PMID 40332447, 2025). "In cancer cells, EPOR signaling modulates mitochondrial biogenesis via pAKT and inducible nitric oxide synthase (iNOS), highlighting its significance in tumor bioenergetics." (PMID 41012526, 2025). "While some studies have suggested that EPO and EPOR promote tumorigenesis in adult and pediatric cancers, others have suggested their tumor-suppressive roles." (PMID 38542288, 2024). "Different tumor types and cell lines have demonstrated the presence of EPOR mRNA transcript in cancer stem cells, with protein expression confirmed in most tumor cell lines." (PMID 39727719, 2024). "As EPOR is expressed on various immune and tumor cells, the interactions between EPO and these cell types requires further study." (PMID 39474425, 2024). "These risks include increased venous thromboembolism events, and tumor progression and recurrence via EPOR activation in tumor cells." (PMID 37208766, 2023). "Across all tumor sections, EPOR expression predicted VDAC1 expression (Pearson’s r = 0.515, p<0.0001)." (PMID 36052260, 2022). "Concerning its role in tumor angiogenesis, EPO facilitates tumor cell survival, tumor growth, angiogenesis, and lymphangiogenesis through EPOR-dependent and EPOR-independent mechanisms." (PMID 36555679, 2022). "Our results show that EPOR controls tumor growth and mitochondrial biogenesis in tumors by controlling the levels of both, pAKT and inducible NO synthase (iNOS)." (PMID 36052260, 2022). "The tumor microenvironment influences the occurrence and progression of tumors; in order to further assess the role of EPOR in the tumor microenvironment, we explored the correlation of EPOR with three scores." (PMID 35359375, 2022).
tumor (continued). "When we immunohistochemically analyzed EPOR and iNOS protein expression in shSCR and shEPOR tumor sections, we observed that both proteins were downregulated in shEPOR tumors." (PMID 36052260, 2022). "We suspected that NO controls mitochondrial biogenesis in the tumor microenvironment and showed that iNOS expression (and thus, NO production) is a key signaling agent that regulates mitochondrial biogenesis via the EPOR in A549 tumors." (PMID 36052260, 2022). "Tryptase-positive MCs were found to be increased in the peritumoural stroma of CMTs with the highest number at the invasive margin, but EPOR (erythropoietin receptor)-positive MCs count was significantly decreased in the tumours." (PMID 35761297, 2022). "Several studies identified pro-stimulating EPO/EPOR effects in tumor cells; however, numerous studies opposed this fact due to the usage of unspecific EPOR antibodies and thus potential absence or very low levels of EPOR in tumor cells." (PMID 30606107, 2019). "In LADC, the altered tumor microenvironment caused by hydrogen peroxide can potentially cause the dysregulation of EGFR, EpoR, and ITGB1 (CD29) signaling pathways." (PMID 31217907, 2019). "Immunohistochemistry results confirmed the truncated IRP1 and overexpressed HIF-2α, EPO and EPOR in tumor cells." (PMID 29534684, 2018). "To determine the clinical relevance of tumor EPO and EPOR expression, we investigated the association of EPO and EPOR expression with several clinical parameters." (PMID 29137269, 2017). "Analysis of tumor material from each of the four subgroups by RNAscope®, using human EPOR probes, showed substantially lower expression of EPOR in the shEPOR+dox subgroup compared to the other three subgroups." (PMID 28418910, 2017). "EPOR knockdown abrogated human tumor cell growth, induced apoptosis through Bim, reduced invasiveness, and caused downregulation of MYC expression." (PMID 28418910, 2017). "Doxycycline-induced knockdown of EPOR significantly increased tumor tripling time from 12.0±1.6 (shSCR−dox), 11.2±1.5 (shSCR+dox), 12.0±1.0 (shEPOR−dox) days to 23.6±2.6." (PMID 28418910, 2017). "Relative cell viability in the dual EPOR/Bim knockdown was greater than in cells with EPOR knockdown alone after 24 hours, suggesting that the survival of tumor cells was partially rescued by Bim depletion." (PMID 28418910, 2017). "Other studies, which found the presence of EpoR on endothelial cells of tumor capillaries as well as reduction of the capillary network by blocking EpoR in vitro, are another confirmation of the participation of Epo in tumor vascularization." (PMID 27543111, 2016). "Epo, and high levels of phosphorylated EpoR, directly accelerates tumor growth through its proliferative and proangiogenic effects." (PMID 27543111, 2016). "This study demonstrated that Epo had enhanced carcinogenesis through increase of EpoR and Flt-1 expression, and thereby contributed to tumor development." (PMID 27543111, 2016). "Our results indicate that response of tumor cells to Epo is variable and depends on the presence of EpoR." (PMID 27543111, 2016). "In control DLD-1 and Ht-29 xenografts, EpoR expression significant negatively correlated with tumor weight (r = −0.524, p < 0.05)." (PMID 27543111, 2016). "In the EpoR-positive cells, Epo treatment can enhance carcinogenesis through increase of EpoR and Flt-1 expression, and thereby contributed to tumor development." (PMID 27543111, 2016). "Most recently, more sensitive and specific reagents, controls and targeted protocols have been generated and the question of EpoR protein expression and function on tumor cell-lines and other cell types has been re-examined." (PMID 25807104, 2015). "Publications have since emerged suggesting functional EpoR is expressed in human tumors and human tumor cell-lines." (PMID 25807104, 2015).
tumor (continued). "For every human tumor that was analyzed for response to rHuEpo and also for EpoR expression, both UT7/Epo and HT29 cell-lines were processed in parallel as experimental controls." (PMID 25807104, 2015). "In vivo, we also reported that EPOR silencing combined with TMZ treatment is more efficient to delay tumour recurrence and to prolong animal survival compared to TMZ alone." (PMID 25544764, 2015). "In this U251 model, EPOR silencing combined with TMZ treatment was more efficient to delay tumour relapse and to increase animal survival compared to TMZ alone." (PMID 25544764, 2015). "Several studies reported that primary tumor tissue and tumor-derived cell-lines express EpoR mRNA transcript and contain EpoR protein as shown by Western blot analysis or immunohistochemistry (IHC)." (PMID 25807104, 2015). "Epo signaling appears to function similarly between erythroid progenitor cells and the Epo/EpoR-expressing HeLa cells in the xenografts; it stimulates tumor cell proliferation and production of embryonic and fetal Hbs with monomeric Mb hemoprotein to survive." (PMID 25874769, 2015). "Analysis of EpoR protein expression was also evaluated by Western blot analysis of 30 tumor tissues lysates from the breast cohort, including 6 Her2 positive tissues." (PMID 25807104, 2015). "EpoR pathway activation was analyzed on viable human tumor cells obtained directly from human tumor tissues representing a range of different primary tumor types." (PMID 25807104, 2015). "In the HeLaX-Ss, the tumor cells and capillary endothelial cells showed strong EpoR immunoreactivity." (PMID 25874769, 2015). "Thus, Epo-signal appears to be involved in tumorigenesis of HeLa cells and in activation of immune cells, and that EMP9 could reduce the expression of Epo and EpoR mRNA and suppress Epo-EpoR signaling in HeLaXs, leading to a loss of viability of the tumor cells and capillary endothelial cells." (PMID 25874769, 2015). "Despite the fact that many tumor cells were confirmed to possess the EPOR, there is still some debate on stimulatory effects of EPO on these cells." (PMID 25426117, 2014). "EPOR expression has been demonstrated by flow cytometry using a specific EPOR antibody in a panel of 29 tumor cell lines, including 18 adherent cell lines." (PMID 25426117, 2014). "Western blot methodologies have been employed extensively in attempts to detect EpoR in extracts from tumors and tumor-cell lines." (PMID 24337485, 2014). "Strikingly, marked invasion of tumor cells into the liver was also abrogated in mice receiving VF/EpoR/sh-c-Myc cells." (PMID 23300995, 2013). "The present study offers a further insight into the tumor biology of the EPO/EpoR axis, with a particular focus on chronic liver injury and its progression to CC." (PMID 23052842, 2013). "In this paper we report that there was undetectable EpoR protein in human normal and tumor tissues from breast, lung, skin, colon and ovary." (PMID 23861852, 2013). "In contrast to these results, there are numerous reports that EpoR protein is expressed in tumors and tumor cell lines." (PMID 23861852, 2013). "Unexpectedly, however, rHuEPOα alone significantly decreased tumor cell proliferation and growth of human xenograft tumors formed by H1975 cells (with the highest EPOR expression among the investigated ADC cell lines)." (PMID 24155958, 2013). "The grade of subcutaneous tumor growth by c-Myc and T58A was comparable to when inoculated with VF/EpoR cells." (PMID 23300995, 2013). "A progressive increase of EPO and EpoR mRNA can already be observed during the fibrotic–cirrhotic development with a peak of expression rising at tumor formation (24.7 ± 9.9-fold increase and 15.5 ± 1.1-fold increase, respectively, for the two genes)." (PMID 23052842, 2013). "The administration of 1% DFMO markedly delayed subcutaneous tumor formation derived from VF/EpoR cells, compared to in mice provided with normal drinking water." (PMID 23300995, 2013).